IFNG (interferon gamma)
Diseases named in the same sentence as IFNG in open-access papers (continued):
Sharing a sentence is not in itself a finding about the gene and the disease.
cancer (continued). "In response to IFNγ release by CD8+ T cells and NK cells, tumor cells activate JAK–STAT signaling and up-regulate immunosuppressive proteins, such as PD-L1 and IDO, which support cancer cell resistance to cytotoxic killing by both T cells and NK cells." (PMID 40663561, 2025). "In addition, in the immune regulatory functions, it enhances the cytotoxic activity of natural killer (NK) cells by secreting interferon-gamma (IFN-γ) and inhibits epithelial-mesenchymal transition (EMT), which is an important event of cancer metastasis." (PMID 39958058, 2025). "Interestingly, CD4+ Texterm phenotype exhibited the highest expression of cytotoxic markers (PRF1, GZMA, GZMB, IFNG, and GNLY), aligning with recent discoveries indicating that cytotoxic CD4+ T cells within tumors can directly kill cancer cells." (PMID 40335494, 2025). "In addition, in the presence of cancer cells, CD64-CR T cells specifically produced high levels of IFNγ." (PMID 39962623, 2025). "These modifications involve expressing immunostimulatory heterologous genes, such as interleukin-12 (IL-12), granulocyte/macrophage colony-stimulating factor (GM-CSF), interferon-gamma (IFN-γ), interleukin-2 (IL-2), or tumor necrosis factor-alpha (TNF-α) in various human cancers." (PMID 40722781, 2025). "To better mimic the TME, we established a tri-culture system comprising cancer cells, BMDMs, and NMFs, without exogenous IFNγ supplementation." (PMID 41511309, 2025). "Furthermore, both drugs suppressed IFNγ-dependent CXCL10 and PD-L1 expression in-vitro in primary human lung cells and human cancer cells." (PMID 40264756, 2025). "In cancer, CD4+ T cells may improve immunity by releasing effector cytokines such as interferon-gamma (IFNγ) and tumour necrosis factor alpha (TNFα), and assisting cytotoxic and antibody responses." (PMID 40560407, 2025). "Coculture killing assay showed ASPG-OE CAR-T cells exhibited increased killing efficacy against ASNS-OE cancer cells by enhancing the expression of granzyme B, interferon gamma, and tumor necrosis factor alpha, whereas ASPG-knockout (KO) CAR-T cells showed decreased cancer cell lysis efficiency." (PMID 40808257, 2025). "Finally, we sought to confirm that INCR1 regulates components of the IFNγ-induced JAK/STAT pathway and the resulting expression of immune checkpoints IDO1, CD274, and PDCD1LG2 in human LUAD cells, as shown in other cancer types." (PMID 40449595, 2025). "Virtually no Annexin V positivity was detected in preparations containing only cancer cells with or without TAP1/2 silencing or after pre-incubation with IFNγ ± TNFα (e.g. (T) 1: (E) 0)." (PMID 40091029, 2025). "In contrast, TAM failed to induce overexpression of IFNG, proposing Ospemifene as an adjuvant therapy to increase the effectiveness of antigen-specific cancer vaccines." (PMID 38659456, 2024). "One plausible explanation is that the elevated expression of TPST2 serves as a negative feedback mechanism for cancer immunosuppression in tumors exhibiting heightened IFNγ." (PMID 39095793, 2024). "Recent studies have demonstrated the importance of IFNγ-IFNγR JAK-STAT signaling for T cell-mediated killing of cancer cells specifically in solid tumors but not in liquid cancers." (PMID 38893085, 2024). "In a previous study of immunodynamics, I explained that (TGFβ)(pSTAT3), through overcoming (IFNγ)(pSTAT1), promoted the occurrence and development of multiple cancer characteristic events (the term “hallmarks” was not used at the time)." (PMID 38807760, 2024). "Enhanced levels of intracellular cytokines, such as interleukin 2(IL2), TNF-α, interferon-gamma (IFN-γ), and IL6, were observed within the memory subpopulation, indicating that IL7 may stimulate a memory immune response targeting cancer." (PMID 38289597, 2024).
cancer (continued). "Additionally, they secrete cytokines like interferon-gamma (IFN-γ) and tumor necrosis factor-alpha (TNF-α), further contributing to cancer cell demise." (PMID 38791916, 2024). "To determine the mechanisms used by lymphocytes to kill cancer cells in BrM following ICB, we investigated whether perforin (Prf) and interferon gamma (IFNγ) are required for the intracranial efficacy of PC blockade." (PMID 39551601, 2024). "Though remaining almost unchanged in responder post-treatment, the expression of IFNγ was primarily within T, natural killer, and cancer cell populations in non-responders." (PMID 39033271, 2024). "The relationship between ncRNAs, trained immunity, and cancer has also paved the way for new treatment options such as β-glucan and Bacillus Calmette–Guérin (BCG), both of which can induce local inflammation and native interferon-gamma (IFN-γ) induction." (PMID 39335585, 2024). "A previous study has shown that lymphocyte-derived IFNγ and TNF within tumors can induce senescence in numerous murine and human cancers, which may be one of the mechanisms for the dormancy." (PMID 38216787, 2024). "In addition to roles in the regulation of IFNγ signaling, TPST2 probably plays additional roles in cancer cells." (PMID 39095793, 2024). "As addressed previously, IFNγ mainly secreted by CD8+ T cells and NK cells, could induce dormancy and G0/G1 growth arrest in cancer cell via STAT1 signaling." (PMID 38216787, 2024). "After 7 days of culture with DEG, murine OT1 CD8+ T cells were more proficient at killing ovalbumin (OVA)-expressing B16F10-OVA cancer cells, while DEG-treated human CD19+ CAR T cells secreted more interferon-γ (IFNγ) and exhibited increased cytotoxicity against CD19+ Raji cells." (PMID 37605057, 2023). "However, it is possible that the effect of IFNγ on IDO2 is cell-type-specific or that higher concentrations of IFNγ are required to induce IDO2, as shown in various human cancer cell lines." (PMID 37408267, 2023). "IFNγ or CAR-T10%MYXV decreases the activity of AKT, which regulates autophagy through phosphorylating Beclin 1, while overexpression of constitutively active AKT in cancer cells abolishes the antitumor activity of CAR-T10%MYXV and VPS34 level." (PMID 37091978, 2023). "Furthermore, the repressed expressions of growth factor TGFb, transcription factor STAT3 and elevated expressions of TNFa, IFNg, CXCR4 together promoted the anti-cancer efficacy." (PMID 37143538, 2023). "Furthermore, feladilimab enhanced the production of IFNγ, IL17, IL10, and TNFα by TCR-activated healthy donor and cancer patient PBMC." (PMID 37593752, 2023). "Additionally, we found that interferon-alpha and interferon-gamma responses were primarily enriched in CD8+ T cells and macrophages in almost all cancers by exploring single-cell characteristics." (PMID 37905956, 2023). "More specifically regarding NK cells, evidence from some cancer studies strongly suggests that CD200 activity directly suppresses the cytotoxic mechanisms of NK cells and their ability to produce interferon-gamma (IFN-γ)." (PMID 36756156, 2023). "Although rare, some cancer cell lines exhibited intrinsic sensitivity to AC484 in the absence of IFNγ, which correlated with increased expression of NFKBIZ, CD274 (which encodes PD-L1), SOCS3, HLA-E, and several other ISGs (top)." (PMID 37794185, 2023). "Multiple studies have demonstrated that many cancer cell lines are not class II inducible by IFNγ due to transcriptional silencing of CIITA." (PMID 37565053, 2023). "Therefore, we focused on upregulated secretome genes that included several known cachexia mediators described in pan-cancer and NSCLC, such as IL6, IFNG, LIF, CCL2, and CSF3." (PMID 36774484, 2023). "Noteworthy among these are IFNγ, which plays a role in both innate and adaptive antitumor response, and IL7, which presents antitumor effects by increasing CD8+ T-cell infiltration, and is also the subject of cancer trials." (PMID 36860652, 2023).
cancer (continued). "Optimized NP formulations delivering 4-1BBL/IL-12or 4-1BBL/IL-12/IFNγ DNA successfully transfect MCC and melanomacells in vitro and in vivo, respectively,resulting in IFNγ-driven upregulation of MHC class I and IImolecules on cancer cells." (PMID 37797944, 2023). "Though type I interferons such as IFNα1b and IFNα2b have been widely used in clinics for cancer treatment, IFNγ (a type II interferon) has not been clinically administrated." (PMID 37671945, 2023). "Furthermore, the repressed expressions of TGFb, STAT3 and elevated expressions of TNFa, IFNg, CXCR4 together promoted the anti-cancer efficacy." (PMID 37143538, 2023). "For cancer cells, we did not detect the expression of IFNα, IFNβ or IFNγ in any of our human and mouse BrM cells." (PMID 37149684, 2023). "No cytotoxic effects (p < 0.05) were observed when cancer cells were treated with the cytokines at the following concentrations: 500 U/mL IFNα, 500 U/mL IFNβ, 20 ng/mL TNFα, and 100 U/mL IFNγ." (PMID 37760788, 2023). "While most studies have focused on the impact of IFNγ on cancer and stromal cells, the consequences of IFNγ on immune cells, in particular T cells, has not been directly and thoroughly addressed in cancer." (PMID 36658158, 2023). "In the pathway analysis, we found that PANoptosis score was positively correlated with IL6-JAK-STAT3 signaling, interferon-gamma response, inflammatory response, IL2-STAT5 signaling, and TNF-a signaling via the NF-kB signaling pathway in 33 diverse cancer types." (PMID 36890219, 2023). "The observation that IFNγ signaling and IRF1 expression are important biomarkers in ccRCC, addressing the importance of the SPOP-IRF1 axis in this cancer type may be of particular interest in future studies." (PMID 37622993, 2023). "Genes in response to interferon gamma, including CCL20, CCL25 and CD74, and antigen presentation-related genes, such as HLA-DPA1, HLA-DRA and HLA-DRB, were significantly upregulated in the cancer cells of immune-rich type tumors." (PMID 36729271, 2023). "These indicated that adaptive immunity, including cytotoxic CD8 T-cells and helper CD4 T-cells with Th1 signature (IFNG, IL12, IRF1), might arise before the carcinoma stage." (PMID 36672367, 2023). "Most importantly, OV+ICB-driven DEMHCPs contain biologically active epitopes that stimulate interferon-gamma responses in cognate CD8 T cells, which may mediate clinically desired antitumor attack and cancer immunoediting." (PMID 34922008, 2022). "The most studied cytokines in cancer therapy are granulocyte-macrophage colony-stimulating factor (GM-CSF), vascular endothelial growth factor (VEGF), interluekin-2 (IL-2), granulocyte colony-stimulating factor (G-CSF), and interferon gamma (IFN-γ)." (PMID 36297474, 2022). "IFNα (1 × 104 IU/mL) was capable of direct cancer cell cytotoxicity in 4/8 (50%) of wtGISTc tested, while no significant cancer cell cytotoxicity was mediated by IFNγ (1 × 103 IU/mL)." (PMID 36142281, 2022). "Due to the presence of molecular aberrations in the IFNγ signaling pathways, many cancer patients do not respond to immune checkpoint blockade strategies." (PMID 36189315, 2022). "In addition, interferon gamma derived from NK cells upregulates MHC I, leading to resistance to the anti‐cancer efficacy of NK cells." (PMID 35355427, 2022). "These APOBEC3 genes are all induced upon IFNγ expression in response to HPV infection, and their genome editing ability is known to increase neoantigen presentation in the context of MHC in these cancers." (PMID 36497170, 2022). "In addition, T-regulatory cells and macrophages can contribute to an immune-suppressed microenvironment through interferon gamma (IFNγ) production, and IFN signaling can contribute to growth suppression in cancer cell dormancy." (PMID 35321751, 2022).
cancer (continued). "Therefore, FBXO44/SUV39H1 inhibition can enhance cancer cell immunogenicity and overcome ICB resistance via the transcriptional regulation of IFNγ signaling." (PMID 34385592, 2022). "On the other hand PD-L1 upregulation by IFNγ can contribute to immune evasion and approaches to combining CAR T cells with PD-1/PD-L1 blockade have produced promising results even in hard-to-treat cancers." (PMID 36189315, 2022). "Unlike monocyte-derived TAM10, cancers use B-MF to mediate escape and metastasis via suppressing antitumor IFNγ+CD4+ T cells." (PMID 36104343, 2022). "In cancer cells, SHP2 inhibition potentiated the response to IFNγ by enhancing JAK-STAT signaling." (PMID 33446805, 2021). "This assay enables to interrogate single cell expression levels of multiple mRNA of interest such as CD4, Cd8α, IFNγ and GZMB and their spatial distribution and can be used to detect, quantitate and evaluate the frequency and function of CAR T cells and cancer cells in tissues." (PMID 34155235, 2021). "Specifically, interactions between CAR-T cells and A549 cancer cells produced 1.36 ng/mL IFNg; meanwhile, the interaction of T cells with cancer cells A549 did not produce any IFNg." (PMID 34189144, 2021). "Despite these efforts, there is still no definite conclusion on the efficacy of IFNg in cancer therapy." (PMID 34835178, 2021). "The binding activates the CD4+ and CD8+ T cells which in turn will produce pro-inflammatory cytokines [respectively tumor necrosis factor (TNF)-α, anti-tumor cytokine interferon-gamma (IFN-γ), Granzyme B, and perforins], leading to the destruction of cancer cells." (PMID 36046144, 2021). "IFNγ signaling is regulated by multiple positive and negative feedbacks, thus playing different or even opposing roles in cancer cells and immune cells." (PMID 34853298, 2021). "In addition to TGFB1 and IL10, gene expression of IFNG, IL6, and CXCL8 were all significantly increased (p < 0.05) in mesenchymal samples for more than half of the cancer types." (PMID 35096592, 2021). "Additionally, we developed a method for coculturing cancer cell spheroids and macrophages under free-floating 3D conditions to investigate the SFV-based delivery of IFNg and to decipher the direct macrophage-inhibitory effects on cancer spheroid growth." (PMID 34835178, 2021). "Previous studies show that other cancer cell lines have comparable total formate efflux under normal cell culture conditions (i.e., without IFNγ): HCT116 = 14–16 fmol/cell/h, IMR90 = 10 fmol/cell/h, HEK293T = 9 fmol/cell/h, and A549 = 0.9 fmol/cell/h." (PMID 33831358, 2021). "In contrast, the pan-cancer-based IFNG gene signature and IFNG expand gene signature failed to predict prognosis." (PMID 34566988, 2021). "Moreover, the ferritin heavy subunit (FTH) produced by cancer cells can activate circulating T cells to secret cytokines such as TNF-α and IFNγ, resulting in increased iron retention in macrophages." (PMID 34796174, 2021). "Interferon gamma (IFNγ) released from cytotoxic T cells activates the JAK–STAT1 pathway, which in turn downregulates the expression of SLC7A11 and SLC3A2 inducing ferroptosis in cancer cells." (PMID 34485382, 2021). "Interferon gamma, IL-6, TNFα, and TRAIL are all secreted signaling molecules that have prominent roles in the regulation of cell death in various cell types, including cancer cells in addition to their immune regulatory functions." (PMID 33375357, 2020).
cancer (continued). "In sum, AP rapidly stimulates the degranulation of cytotoxic granules and the production of the anti-cancer cytokines IFNγ and TNFα in Vγ9Vδ2 T cells but not within other T cells." (PMID 32604868, 2020). "GSK3β inhibition prevents IFNγ-induced IDO, including in cancer cells, and dendritic cells." (PMID 33375613, 2020). "Thus far, only a few cancer cell lines that express TDO constitutively are known, while many cell lines express IDO1 upon stimulation with IFNγ." (PMID 33584686, 2020). "IFNγ was more effective than radiation in inducing MHCI on the cancer cells, and we were not able to further increase the dose of radiation to attempt to amplify MHCI induction due to its cytotoxic effect on the cancer cells." (PMID 32355214, 2020). "We explored whether Th1-cytokines, IFNγ and, TNF-α, can modulate the KYN downstream metabolites such as 3-HK, 3HAA, and AA in cancer cells." (PMID 32117720, 2020). "Seminal studies have shed light on T-cell exhaustion in human cancers, where CD8 T cells lose proliferative capacity, the ability to produce tumor necrosis factor (TNFα), interleukin-2, and interferon-γ (IFNγ), and upregulation of inhibitory checkpoint receptors, such as PD-1 and CTLA-49–11." (PMID 31804466, 2019). "Cytokines such as IFNγ, TNFα, and TLR3 ligands could induce production of these chemokines by cancer cells which then serve to recruit T and NK cells." (PMID 31627733, 2019). "We hypothesized that sensitivity of cancer cells to IFNγ is a major regulator of the TME, and that altering the sensitivity of the cancer cells would regulate the response of tumors to checkpoint inhibition." (PMID 31133614, 2019). "Intriguingly, MEK inhibitor selumetinib suppressed the IFNγ‐induced development of low‐adherent cells as well as the establishment of re‐adherence (right), indicating crosstalk between IFNγ and MEK/Erk signalling pathways in the anoikis‐resistant cancer cell survival." (PMID 30919591, 2019). "Defects involved in IFNγ signaling and antigen presentation pathways, as tumor-intrinsic alterations, can lead to resistance to cancer immunotherapy, which explains why immunotherapy is not effective in some cancer patients." (PMID 31379886, 2019). "All of these cells play a crucial role in cancer cell elimination; therefore, increases in the numbers of CTLs, NKT, and NK cells together with improvement in IFNγ production all helped to enhance the eradication HCC cells, as shown in the results of our study." (PMID 31776459, 2019). "Indeed, melatonin is effective in restraining neoplastic growth in various tumors and cancers, including CRC, by enhancing TH cell immune response by producing interleukin (IL)-2, IL-10, and interferon-gamma (IFN-γ)." (PMID 31637261, 2019). "Moreover, IFNγ was significantly upregulated when mice treated with anti-CD47, suggesting that while TAMs are engulfing cancer cells, the antigen presenting function of the macrophages induces CD8+ T cells to further eradicate cancer cells." (PMID 30062558, 2018). "Even though it's pivotal importance in cancer immunotherapy, IFNγ has not been approved by FDA to treat patients with a variety of cancer types, except malignant osteoporosis." (PMID 30039553, 2018). "In agreement with the existing evidence, treating whole blood of patients with cancer with IL-2, IL-15 and IL-21 markedly improved the antigen-specific IFNγ response regardless of existing immunosuppression, thereby suggesting clinical applicability." (PMID 29970101, 2018). "IFNγ is known to increase expression of MHC-I, together with chaperones involved in antigen processing and presentation, and plays an important role in inflammatory immune responses to viruses and cancer." (PMID 30026743, 2018). "Interestingly, the pro-inflammatory cytokine, IFNγ, which is secreted by CD8+ T cells, induces cytotoxicity against cancer cells." (PMID 30062558, 2018).